ENSG00000275307
Gene: Miscellaneous RNA gene on chromosome 22 (30,973,417 to 30,973,597, forward strand). Ensembl gene ENSG00000275307.
Gene Ontology:
Biological process: regulation of eye photoreceptor cell development